CFTR (CF transmembrane conductance regulator)
Diseases named in the same sentence as CFTR in open-access papers (continued):
Sharing a sentence is not in itself a finding about the gene and the disease.
cystic fibrosis (continued). "Chemically modified cystic fibrosis transmembrane conductance regulator (CFTR) mRNA was used to treat cystic fibrosis in CFTR knockout mice." (PMID 39760094, 2024). "Cystic fibrosis is a life-limiting genetic disease affecting the lungs and multiple other organs that is caused by pathogenic variants in the gene encoding the CF transmembrane conductance regulator (CFTR) protein." (PMID 39293854, 2024). "Cystic fibrosis is a genetic condition that affects the cystic fibrosis transmembrane conductance regulator (CFTR) protein." (PMID 38949023, 2024). "One of the most studied chloride ion channels in cancer is the cystic fibrosis transmembrane conductance regulator (CFTR), which is mutated in patients with cystic fibrosis." (PMID 37984883, 2024). "Cystic fibrosis is characterized by repeated cycles of infection and inflammation resulting from dysfunctional CF transmembrane conductance regulators and the accumulation of thick and sticky mucus lining the airways." (PMID 38690371, 2024). "Today, more than 90% of people with cystic fibrosis (pwCF) are eligible for the highly effective cystic fibrosis transmembrane conductance regulator (CFTR) modulator therapy called elexacaftor/tezacaftor/ivacaftor (ETI) and its use is widespread." (PMID 38564694, 2024). "Cystic fibrosis, an inherited autosomal recessive disease with a chronic course and poor prognosis, is characterized by a defective gene that encodes the cystic fibrosis transmembrane conductance regulator (CFTR) protein." (PMID 39194088, 2024). "Cystic Fibrosis is the most common autosomal recessive disease in the Caucasian population caused by mutations in the gene encoding for the Cystic Fibrosis Transmembrane conductance Regulator (CFTR), an ion channel that regulates the ionic content of luminal fluid." (PMID 38721278, 2024). "Cystic fibrosis is a genetic disease in which cystic fibrosis transmembrane conductance regulator (CFTR) anion channels fail to move Cl– and HCO–3 through cell membranes." (PMID 39254087, 2024). "Cystic fibrosis is a disease caused by the alteration of a single gene, the CFTR gene (cystic fibrosis transmembrane conductance regulator)." (PMID 39408260, 2024). "Cystic Fibrosis is a genetic disease due to loss-of-function mutations of the CFTR channel." (PMID 39624835, 2024). "Although the clinical, ultrasound, and radiological appearance is different for simple versus complicated meconium ileus, the definitive diagnosis of cystic fibrosis is established based on genetic testing or biochemical alterations of the CFTR." (PMID 38893705, 2024). "The penetrance of CFTR is complex, ranging from autosomal dominant in the case of bronchiectasis (OMIM: 211400) to autosomal recessive in the case of cystic fibrosis, with expressivity being variant-dependent." (PMID 39062917, 2024). "Given that cystic fibrosis is a life-threatening disease, CFTR gene testing and counseling for CBAVD patients and their spouses are particularly important." (PMID 39402445, 2024). "A partial restoration of F508del-CFTR-mediated Cl− transport in primary cultures of human cystic fibrosis airway epithelia was achieved through the depletion of the ubiquitin ligase FBXO2." (PMID 38888668, 2024). "Cystic Fibrosis (CF; MIM: 219700) is a multi-system autosomal recessive rare disease caused by pathogenic, ‘CF-causing’, variants (henceforward mutations) in the Cystic Fibrosis Transmembrane Conductance Regulator (CFTR; MIM: 602421) gene." (PMID 38744777, 2024). "Cystic fibrosis is the most common life-shortening genetic recessive disease in Caucasian people, resulting from a mutation in a gene located on chromosome 7 (7q31.2) that encodes a protein termed Cystic Fibrosis Transmembrane Conductance Regulator (CFTR)." (PMID 38892373, 2024).
cystic fibrosis (continued). "The introduction of VX-770 (ivacaftor, Kalydeco©) into clinical use for the treatment of cystic fibrosis was the first therapy targeting the underlying cause of the disease: the dysfunction of the cystic fibrosis transmembrane conductance regulator (CFTR) ion channel." (PMID 39595555, 2024). "Mutations in the cystic fibrosis transmembrane conductance regulator (CFTR) that impair this ion channel’s function result in the disease cystic fibrosis." (PMID 38352056, 2024). "This approach is reminiscent of the fixed-dose triple combination therapy used to treat protein misfolding in cystic fibrosis, which involves co-administration of two orthogonal PCs with a CFTR channel gating potentiator." (PMID 38712038, 2024). "The human homologue, TMEM16A, is of interest as a therapeutic intervention for cystic fibrosis, where it is proposed that modulation of TMEM16A function can mitigate the symptoms caused by loss of CFTR." (PMID 39461969, 2024). "A notable example that has reached clinical development is based on rescuing the consequences of the common CFTR Phe508 deletion in cystic fibrosis patients." (PMID 39013852, 2024). "Another study examined approaches to reducing the immune response to HD-Ad to extend the duration of CFTR gene expression in the airways of mice, which is especially important for treating cystic fibrosis." (PMID 39596526, 2024). "TNFα and IL-17–asscoaited inflammatory responses increase CFTR modulator efficacy, suggesting reconsideration of pros and cons of suppressing inflammation in cystic fibrosis." (PMID 38888974, 2024). "This response was believed to be due to the calcium-dependent activation of a chloride channel distinct from CFTR, as it was also observed in patients with cystic fibrosis." (PMID 39408877, 2024). "Other studies have shown that inhibition of SUMOylation can attenuate cystic fibrosis via CFTR, confirming that CFTR is a vital therapeutic target against cystic fibrosis." (PMID 39697538, 2024). "Cystic fibrosis is caused by mutations in the cystic fibrosis conductance regulator (CFTR), a chloride and bicarbonate channel that plays important roles in regulating the hydration and pH of epithelial secretions in the lung, pancreas, gallbladder, liver, and intestine." (PMID 39687022, 2024). "In this article, we present a concise overview of thoracic imaging in paediatric patients with cystic fibrosis in the context of CFTR modulator therapy." (PMID 38397368, 2024). "A sweat Cl– test, which is generally used to assess CFTR protein function in individuals suspected of having cystic fibrosis, was conducted to compare CFTR function." (PMID 38877637, 2024). "Next, we performed anti-CFTR immunoblotting in cystic fibrosis bronchial epithelial cell lines (CFBE41o−) expressing either F508del-CFTR or WT-CFTR." (PMID 38427726, 2024). "Cystic fibrosis is an autosomal recessive disease caused by a defect in a gene on the long arm of Chromosome 7 which codes for the cystic fibrosis transmembrane conductance regulator (CFTR), a chloride channel on epithelial surfaces." (PMID 38893705, 2024). "CFTR is a transmembrane regulator of cystic fibrosis and is expressed in various organs, including the pancreas, lungs, ducts of the perspiratory glands, and other tissues." (PMID 39897071, 2024). "This review presents examples of using intestinal organoid models for assessments of the two most common and two rare CFTR CAs in individuals with cystic fibrosis in Russia." (PMID 38392563, 2024). "A notable example is MRT5005, an mRNA therapy designed for cystic fibrosis, which has entered clinical trials as a protein replacement therapy targeting the cystic fibrosis transmembrane conductance regulator (CFTR) protein." (PMID 39795966, 2024). "The delivered gene cystic fibrosis transmembrane conductance regulator (CFTR) mRNA was highly expressed after nebulization in cystic fibrosis pigs." (PMID 39199292, 2024).
cystic fibrosis (continued). "Cystic fibrosis is a life-threatening autosomal recessive genetic disorder caused by mutations in the CF transmembrane conductance regulator (CFTR) gene, encoding a cAMP-regulated chloride channel expressed in the apical membrane of epithelial cells of different tissues." (PMID 38247630, 2024). "For instance, cystic fibrosis is often caused by a specific mutation, ∆F508, in the CFTR gene." (PMID 39726634, 2024). "Although the principal airway phyla are well known through OTU studies of whole communities, previous attempts at culture have been limited to patients with Cystic Fibrosis 68–70, a disease in which CFTR mutations induce major changes in the airway mucosal fluid and host environment." (PMID 38347162, 2024). "Another example is cystic fibrosis (CF, OMIM # 219700), a common autosomal recessive genetic disease caused by mutations to the cystic fibrosis transmembrane conductance regulator (CFTR) gene, among which 10% are nonsense mutations." (PMID 38959711, 2024). "AAV2 vectors carrying cystic fibrosis transmembrane conductance regulator (CFTR) complementary DNA (cDNA) have also been employed for cystic fibrosis." (PMID 39199292, 2024). "Cystic fibrosis is a fatal autosomal recessive disorder caused by the loss of function mutations within a single gene for the Cystic Fibrosis Transmembrane Conductance Regulator (CFTR)." (PMID 38542363, 2024). "Some CFTR correctors, like those approved for the treatment of the ΔF508 mutation in cystic fibrosis (VX661, VX445, and VX809), exert their action as true pharmacological chaperones, which bind and stabilize the mutated CFTR." (PMID 39769077, 2024). "Linaclotide stimulates duodenal bicarbonate secretion upon loss of CFTR function by increasing membrane trafficking and activity of DRA, indicating potential therapeutic value in cystic fibrosis." (PMID 38869953, 2024). "The reduction in CFTR function following long-term β2-agonists use seems to have little consequences in healthy individuals, and it appears to be more significant in cystic fibrosis, especially on modulatory therapy such as pharmacologic F508del correction." (PMID 39408565, 2024). "In individuals with cystic fibrosis, the CFTR chloride channels, which are responsible for recycling chloride ions in the ducts, are defective." (PMID 39529803, 2024). "In this regard, numerous studies on the CFTR ΔF5408 mutant, which is responsible for cystic fibrosis, have accumulated evidence that the strategy of combining multiple compounds is very successful in fully rescuing the processing of CFTR mutants." (PMID 38786040, 2024). "By correcting these mutations, researchers hope to restore the proper function of the CFTR protein and improve outcomes for patients with cystic fibrosis who have developed resistance to existing treatments." (PMID 38877530, 2024). "In cystic fibrosis due to F508del CFTR, the CFTR corrector VX-809 increases the binding affinity between NHERF1 PDZ1 and the mutant protein and its membrane stability." (PMID 38731904, 2024). "Cystic fibrosis is a monogenic syndrome caused by variants in the CF Transmembrane Conductance Regulator (CFTR) gene, affecting various organ and systems, in particular the lung, pancreas, sweat glands, liver, gastrointestinal tract, vas deferens, and vascular system." (PMID 39329970, 2024). "CF is caused by a variety of different mutations in the cystic fibrosis transmembrane conductance regulator (CFTR) and is characterized by the predictable development of mucus obstruction, unconventional inflammation, and chronic bacterial infection of the lungs." (PMID 39950136, 2024). "p.Asn1303Lys (N1303K) is a common missense variant of the CFTR gene, causing cystic fibrosis." (PMID 38474016, 2024).
cystic fibrosis (continued). "Cystic fibrosis (CF; OMIM #219700) is an autosomal recessive disorder caused by pathogenic variants in the nucleotide sequence of the CFTR gene (OMIM *602421)." (PMID 39529847, 2024). "Various vascular responses involve Cl− currents, indicating the existence Cl− channels such as transmembrane protein 16 (TMEM16)/anoctamin (ANO), bestrophins, voltage-gated Cl− channels (CLCs), cystic fibrosis transmembrane conductance regulator (CFTR)." (PMID 38573803, 2024). "Importantly, the proinflammatory activation mechanisms for NFκB and ENaC signaling in CF are well known, and depend on the presence of inactivating mutations in CFTR, the Cystic Fibrosis Transmembrane Conductance Regulator9." (PMID 39043712, 2024). "Comprehensive annotation of 804 of these CFTR mutations (April 2023) is available from the CFTR2 online global database hosted by Johns Hopkins University and supported by the US Cystic Fibrosis Foundation." (PMID 39458161, 2024). "In recent years, a major breakthrough in cystic fibrosis research was made with the publication of experimental 3D structures of full-length CFTR proteins, initially from zebrafish and subsequently from humans, solved using cryo-EM." (PMID 39770445, 2024). "CF is a monogenic disease with an autosomal recessive inheritance, caused by mutations in the gene coding the cystic fibrosis transmembrane conductance regulator (CFTR) protein, responsible for impaired chloride and bicarbonate secretions across epithelial cell apical membranes." (PMID 37780857, 2023). "Notably, IR, inflammation and infertility are also features of cystic fibrosis, a chronic inflammatory disease due to cystic fibrosis transmembrane conductance regulator (CFTR) loss of function." (PMID 37256493, 2023). "Defects in CFTR, as seen in cystic fibrosis, a genetic disease caused by mutations of CFTR, lead to disturbance in epithelial homeostasis and thus complications of epithelium-enriched organs, such as airway obstruction/inflammation, gastrointestinal problems, and reproductive failures." (PMID 37628754, 2023). "Biallelic germline loss of CFTR causes the hereditary life-shortening disease, cystic fibrosis." (PMID 36765944, 2023). "Cystic fibrosis is an autosomal recessive disorder caused by mutations in the Cystic Fibrosis Transmembrane conductance Regulator (CFTR) gene, which encodes for the CFTR protein." (PMID 37833986, 2023). "A survey that sampled 524 cystic fibrosis researchers worldwide showed that CFTR modulators, CFTR modulator combinations, and fixing/replacing the CFTR gene are all viable options in treating cystic fibrosis in the future." (PMID 36983631, 2023). "Cystic Fibrosis is a heritable autosomal recessive pathology caused by the malfunction of a chloride transporter, Cystic Fibrosis Transmembrane Conductance Regulator (CFTR), which causes lung impairment." (PMID 37190584, 2023). "Cystic fibrosis is an autosomal recessive disorder caused by a mutation in the cystic fibrosis transmembrane conductance regulator (CFTR) gene which results in thickened mucus secretions in the airways of the lungs and the ducts of the pancreas, and impaired mucocillary clearance." (PMID 35275333, 2023). "Cystic fibrosis is one prominent example of a genetic disease–causing mutation in the CF transmembrane conductance regulator (CFTR) protein, which ultimately leads to defective mucus clearance and heavy bacterial colonization of the lung by various species that develop antibiotic resistance." (PMID 37781922, 2023). "As is discussed later, Phase I/II clinical trials are ongoing for the inhalation of LNPs for the treatment of cystic fibrosis via the protein target CFTR." (PMID 36768539, 2023). "Clinical management of cystic fibrosis has been greatly improved by the development of small molecule modulators of the CF transmembrane conductance regulator (CFTR)." (PMID 37137509, 2023).
cystic fibrosis (continued). "For example, recently, we used smFRET to study the misfolding and drug rescue mechanism of the cystic fibrosis transmembrane conductance regulator (CFTR), an ion channel protein that is defective in people with cystic fibrosis (pwCF)." (PMID 37845199, 2023). "CFTR functions, however, can be easily assessed in rectal biopsies and rectal organoid cultures offering personalized treatment options in patients with cystic fibrosis." (PMID 36609875, 2023). "The CFTR (cystic fibrosis transmembrane conductance regulator) protein is a chloride channel in the plasma membrane of epithelial cells, and certain CFTR mutations are the monogenic cause of cystic fibrosis." (PMID 36835433, 2023). "It has been suggested that in vitro studies of the rescue effect of CFTR modulator drugs in nasal epithelial cultures derived from people with cystic fibrosis have the potential to predict clinical responses to the same drugs." (PMID 37190083, 2023). "Cystic fibrosis is characterized by mutations in the CF transmembrane regulator (CFTR) gene." (PMID 36738326, 2023). "The R1283G CFTR variant has negligible levels of chloride channel activity (ΔIsc = 0.7 ± 0.1 μA/cm2) which corresponds to less than 0.6% of WT CFTR function observed in Cystic Fibrosis Bronchial Epithelial (CFBE) cells." (PMID 37649273, 2023). "In patients with pancreatitis from CF and some remaining pancreatic function, treatment of some genetic variants in the cystic fibrosis transmembrane conductance regulator (CFTR) with CFTR modulators resulted in highly significantly improved lung function and weight gain in almost all patients." (PMID 39132652, 2023). "Ivacaftor is a potentiator (it enhances the chloride transport) of the cystic fibrosis transmembrane conductance regulator (CFTR), and it is the first drug to be licensed for use that treats an underlying cause of cystic fibrosis." (PMID 36674441, 2023). "Russian adult male patients with cystic fibrosis and CBAVD syndrome share a similar spectrum of pathogenic CFTR gene variants; however, some of the variants and genotypes dramatically differ between these patients’ groups." (PMID 38003474, 2023). "We acknowledge Dr. Tim Jensen and the Antibody Distribution Program of the North American Cystic Fibrosis Foundation for providing CFTR-specific antibodies." (PMID 36778025, 2023). "Preclinical and clinical studies are ongoing for the inhalation of LNPs for the treatment of cystic fibrosis via the protein target CFTR." (PMID 36768539, 2023). "The Ussing assay has served as a gold standard for the measurement of CFTR function in drug development for cystic fibrosis." (PMID 37680748, 2023). "The HD-Ad-CFTR also demonstrated transduction of human airway basal cells from cystic fibrosis patients and restoration of CFTR channel activity." (PMID 36992407, 2023). "According to the experimental evidence, NV molecules restore CFTR protein expression after the treatment of in vitro cystic fibrosis model systems and Shwachman–Diamond model systems." (PMID 37894764, 2023). "Knowledge of CFTR (cystic fibrosis transmembrane regulator) dysfunction on epithelial cells and genetic mechanisms in cystic fibrosis has led to the development of potent symptomatic and mutation-specific drugs." (PMID 37408761, 2023). "Ussing chamber studies of intestinal organoid monolayers compare favorably to established preclinical tools to assess individual responses to CFTR modulator drugs in people with cystic fibrosis." (PMID 37024122, 2023). "Cystic fibrosis transmembrane regulator (CFTR) modulators have led to dramatic improvements of respiratory symptoms and quality of life in patients with cystic fibrosis." (PMID 36738326, 2023). "Pathogenic CFTR (cystic fibrosis transmembrane conduction regulator) gene variants are a cause of cystic fibrosis, CF (OMIM#219700), and CFTR-related disorders (CFTR-RD), particularly, congenital bilateral aplasia of vas deferens (CBAVD)." (PMID 38003474, 2023).